MMP2 (matrix metallopeptidase 2)
Diseases named in the same sentence as MMP2 in open-access papers (continued):
Sharing a sentence is not in itself a finding about the gene and the disease.
tumor (continued). "3D mono-cultured BMSC spheroids secrete merely the inactive pro-enzyme of MMP-2 (66 kDa) and no MMP-9, whereas mono-culture tumor spheroids show very little or no expression and secretion of MMP-2 and MMP-9." (PMID 36674806, 2023). "Identical results were obtained for tumor tissue patients with adjuvant chemotherapy (TIMP1 (p = 0.3108); MMP2 (p = 0.6402); MMP9 (p = 0.5738)) and without adjuvant chemotherapy (TIMP1 (p = 0.2654); MMP2 (p = 0.69); MMP9 (p = 0.5649))." (PMID 37509417, 2023). "Besides, the conjugate showed a high antitumor effect in SGC-7901 tumor model with a tumor inhibition rate of 59.57%, and which might be mediated by increasing the levles of TNF-α, Bax and Caspase-3 and reducing the levels of CD34, VEGF, MMP-2, MMP-9 and Bcl-2." (PMID 36463199, 2022). "Unlike common anticancer agents, BB94 is a potent extracellular inhibitor of MMP-1, MMP-2, MMP-3, MMP-7, and MMP-9, and thus, it should be released in the extracellular space rather than in tumor cells." (PMID 35440570, 2022). "Here, we show that even though URB447 slightly influences the secretion of MMP-2 and MMP-9 in both tumor models, there is no significant change after 24 h." (PMID 36297277, 2022). "Irrespective of its origin, MMP-2 degrades the ECM and thus induces remodeling of the matrix and subsequent migration of the tumor cell." (PMID 34429501, 2021). "Although we did not evaluate macrophage phenotype, VEGF-A, MMP-2, and MMP-9 levels reflect tumor microenvironment changes as they are produced by M2 macrophages." (PMID 34194604, 2021). "Collectively, the pathway analysis of MMP2/MMP9 co-expressed genes showed their involvement in EMT and Immune system pathways, emphasizing their importance in tumor progression, although the mRNA expression levels were not directly correlated with prognosis." (PMID 34830271, 2021). "While VSCC showed the negative expression of MMP2 on tumor cells and a slight expression on stromal cells, SCC presented the high expression of MMP2 on both tumor and stroma areas." (PMID 35008304, 2021). "In tumor tissue with overexpressed MMP-2, tumor imaging and triggered drug release occurred due to the hydrolysis of the MMP-2-responsive peptide substrate, while in the absence of MMP-2, no fluorescence and drug release occurred." (PMID 33562376, 2021). "Two days later, we injected F1 cells that OE OVA in the presence or absence of Mmp2 (F1 OVA, F1 Mmp2-OE OVA, or F1 Mmp2 KO OVA cells) and followed tumor growth kinetics." (PMID 34032639, 2021). "We demonstrated that the enzymatic product of ALDH1A2, retinoic acid (RA), modulated the expression and activity of MMP-2 and MMP-9 in macrophages, but not in GBM tumor cells." (PMID 34572134, 2021). "In our study, mRNA levels for VEGF, NFkB, CDKN2a-p16, MMP2, MMP9 genes were increased in the tumor microenvironment from PNT rats, but the results were not significant because of the high cell heterogeneity found between OSCC samples of both groups." (PMID 32499868, 2020). "The effect of this nanoconjugate in tumor-bearing mice show great promise, showing an enhanced anti-tumor effect when compared to free DOX and AuNPs without the MMP-2 substrate." (PMID 31475143, 2019). "CLC-3, MMP2 and annexinA2 expression in MIA PaCa-2, BxPC-3 and PC-3 tumor lysates: lack of correlation with therapeutic activity." (PMID 31208428, 2019). "Similar results were found in our previous studies concerning other gastrointestinal neoplasms, where the serum MMP-2 and TIMP-2 levels were not correlated with tumor stage." (PMID 30719232, 2019). "Our previous studies performed on GC, CC and EC patients have also revealed that the serum levels of MMP-2 and TIMP-2 did not significantly correlated with clinico-pathological parameters of tumor." (PMID 30719232, 2019). "Further, the use of MMP-2-selective near-infrared probes showed that MMP-2, as opposed to other MMPs expressed in the tumor–bone microenvironment such as MMP-13, were selectively inhibited by the administered BMMPIs." (PMID 29874869, 2018).
tumor (continued). "In a murine model of breast cancer, IL-12 treatment reduced the levels of MMP-9, but not MMP-2, and it also reduced tumour cell production of VEGF by up-regulation of IFN-γ production leading to the suppression of tumour angiogenesis." (PMID 29555826, 2018). "Activities of MMP-2, MMP-9, and uPA in plasma in the tumor control mice were significantly higher than those in the normal control (p < 0.05)." (PMID 29794990, 2018). "MMP-2 and TIMP-1 were mostly expressed in the proximity of blood vessels and inflammatory cells in tumour-invaded areas, but was not seen in tumour-free areas." (PMID 29623449, 2018). "Thus, hYSK1 is necessary as a trigger for inactivating p16INK4a and activating MMP-2 during tumor migration, suggesting that hYSK1 is a specific negative regulator of the tumor suppressor p16INK4a and may represent a novel molecular target for reactivation of tumor suppressor genes in humans." (PMID 29179500, 2017). "With multivariate analysis in non-muscle invasive bladder cancer (NMIBC) age, tumor grade portended a worse PFS, while age, tumor grade, nodal status, MMP2, RB and PAI-1 expression portended a worse OS." (PMID 29245935, 2017). "Coculture of the M1 with Hepa1-6 cells showed a remarkable inhibition of migration and invasion of the tumor cells and decreased expressions of matrix metalloproteinase (MMP)-9 and MMP-2 without notable apoptosis of Hepa1-6 cells." (PMID 28243242, 2017). "In GBMs, most gemistocytic tumor cells showed intense MMP-2 membrane expression, whereas multinucleated giant cells generally were negative or only weakly expressed MMP-2." (PMID 28234925, 2017). "We further determined the expression levels of MMP2 and MMP9 in our NSCLC cohort; the results revealed that the expression level of MMP9 but not MMP2 was correlated with MIAT to express highly in tumor tissue and advanced stage." (PMID 29228680, 2017). "Baseline (b) MMP2 and MMP9 serum levels were independent from patient characteristics and circulating tumor or endothelial cells, and were not correlated to pCR." (PMID 26921265, 2016). "These patient tumor samples are determined as eIF4E, VEGF-C, MMP-2 and E-cadherin positive or negative, respectively." (PMID 27907907, 2016). "Tumor and non-tumor samples differed significantly in the expression of 10/22 genes: CCNB1, CLDN4, CLDN6, MMP2, MUC1 (all: p < 0.05), BAG1, SERPINB3 (all: p < 0.01), CD44 (standard variant), MKI67, and MYBL2 (all: p < 0.001)." (PMID 27542596, 2016). "Radiation did not increase the levels of MMP-2 and −9 in the mammary glands that were implanted/not implanted with the D2A1 tumor." (PMID 27282478, 2016). "However, matrix metalloproteinases (MMPs) including MMP-2 and MMP-9 showed significant decrease after ApoA-1 treatment in both two cell lines, which indicating ApoA-1 might inhibit CTC formation via impairing extracellular matrix degradation properties of tumor cells." (PMID 27683106, 2016). "Our study reveals that EMP3 contributes to tumor aggressiveness by MMP-9 and uPA, but not MMP2, on the PI3K/AKT pathway in HCC cells." (PMID 26472188, 2015). "Subsequently, MMP-9 was found overexpressed in the tumor tissue (identified by GFP staining) and not MMP-2 (data not shown)." (PMID 26588686, 2015). "We showed a role for FABP5 modulation of MMP9 secretion, and not MMP2, in TNBC cells, which plays an important role in degrading the extracellular matrix and the invasion of tumor cells." (PMID 25779666, 2015). "Some MMPs, like MMP-2, MMP-9, and MMP-14, can act both as positive and negative regulators of angiogenesis in tumor vasculature." (PMID 24578639, 2014). "Their patterns of immunostaining, unlike those of MMP-2 and MMP-9, are very likely to afford an indication of the invasion potential of the tumour." (PMID 26019601, 2014).
tumor (continued). "Our preliminary data shows that the MMP-2, MMP-9, p-AKT, pERK, pMAPK, and JNK were increased significantly in transfected SAOS-2 tumor cells, while caspase-3 and Ki-67 did not change significantly (data not shown)." (PMID 25300797, 2014). "The results showed that MMP-2 and MMP-9 had similar expression patterns in the tumour cells with no changes in the immunoreactivity during tumour progression." (PMID 26019601, 2014). "Bands corresponding to latent MMP-9 and MMP-2 were clearly detected in all tumor samples, whereas active forms of MMP-9 and MMP-2 showed less distinct bands or no bands in some samples." (PMID 24778099, 2014). "In conclusion, we demonstrated that in human MFH cells DcR3 may increase tumor progression as a decoy, promoting cell proliferation via inhibition of FasL-induced apoptosis and as a non-decoy, regulating cell migration and invasion by MMP-2 activation via the PI3K/Akt pathway." (PMID 23817777, 2013). "HSA/TIMP-2 has no inhibitory effect on MMP-2 activity in vitro and in vivo; nevertheless HSA/TIMP-2 demonstrated a prominent anti-proliferation effect on tumor cells in cancer xenografts." (PMID 22545131, 2012). "In a first step, the BM of an existing vessel is degraded by MMPs that are expressed by ECs, such as MMP-1, MMP-2, MMP-9, and MT1-MMP/MMP14, at which MMP-9 is required for tumor vasculogenesis rather than angiogenesis." (PMID 21941547, 2012). "Our results show that HSA/TIMP-2, which does not inhibit MMP-2 activity or MT1-MMP expression in vivo, acts to promote anti-tumor and anti-angiogenesis activity through the downregulation of MMP-2 expression." (PMID 22545131, 2012). "As tumours progressed, MMP-9 expression increased in tumour epithelium and stroma, while the changes in MMP-2 expression in tumour cells was not as obvious as MMP-9." (PMID 23107277, 2012). "In summary, indicators of tumour and host biology such as Gas6, CD68 and Notch are helpful for improving the prediction of prognosis after NSCLC, but MMP2 and Cox2 were of no clinical value in the present study." (PMID 21794149, 2011). "Transcript levels of MMP2, MMP9 and IL-17A were measured in another 50 pairs (including tumor and related non-tumor tissues) HCC samples." (PMID 21760911, 2011). "Stromal cell are often recruited by tumor cells via extracellular matrix metalloproteinase inducer to enhance invasion and stimulate the production of MMP-1 and MMP-2, again unlike the suppression of migration and MMPs reported here." (PMID 21637818, 2011). "Particularly remarkable is the presence of more active MMP-2, but not of active MMP-9, in the tumour tissue homogenates." (PMID 16538217, 2006). "In the patient group presenting with a progesterone receptor-negative tumour, the survival rate of the MMP-2-positive cases was 58% while it was 95% in MMP-2-negative cases after 10 years of follow-up (P=0.005)." (PMID 14520459, 2003). "The matrix metalloproteinases MMP-2 (72 kDa gelatinase) and MMP-9 (92 kDa gelatinase), which play a key role in invasion in other tumours, are not affected by RA." (PMID 10507760, 1999). "Positive expression of MMP-2 in tumour epithelium and of MMP-9 in tumour-infiltrating macrophages were both independent of tumour stage and were without correlation with survival time." (PMID 9310250, 1997). "Importantly, a negative correlation between MMP-2 and CD8+ T cell infiltration was observed, reinforcing the potential role of MMP-2 in promoting an immunosuppressive tumor microenvironment by limiting CD8+ T cell infiltration." (PMID 40611940, 2025). "On the other hand, the same investigation found that MMP-2 and MMP-9 levels remained constant across OSCC stages, arguing that they could not be used as suitable surrogate marker of tumor-invasiveness potential." (PMID 37445908, 2023).
tumor (continued). "Similarly, a lack of correlation was confirmed for the patients who had tumor cells in the surrounding lymph nodes as compared to those whose lymph nodes were free (TIMP1, p = 0.6652; MMP2, p = 0.5166; MMP9, p = 0.9766; collectively, p = 0.8416)." (PMID 37509417, 2023). "Furthermore, gene and protein analyses demonstrated that HA-GC-DOX/CXB markedly increased caspase-3 while markedly decreasing NF-kB, MMP-2, and COX-2 in tumour tissues—all without manifesting any hepatotoxicity." (PMID 36559281, 2022). "Compared to non-sensitive counterparts, this MMP2 sensitivity of PEG2000-peptide-PTX micelle showed superior cell internalization, cytotoxicity, tumor targeting, and antitumor efficacy, which is promising for effective intracellular drug delivery in cancer therapy." (PMID 34249894, 2021). "Furthermore, results of immunohistochemistry showed that the expression levels of Ki-67, MMP-2 and STK39 in tumor of STK39 knockdown group were lower than that in negative control group (p < 0.01)." (PMID 34519635, 2021). "Furthermore, the inhibition of KLF5 markedly decreased MMP-2, MMP-9 and VEGF, which further confirms the role of KLF5 not only in tumor growth, but also in migration and angiogenesis and overall metastatic potential of PTC cells." (PMID 33430300, 2021). "Thus at the doses of inhibiting tumor metastasis RGDV-gemcitabine, but not gemcitabine, effectively decrease of serum MMP-2 and MMP-9 of C57BL/6 mice." (PMID 32978501, 2020). "MMP-2 and Nck1 (non-catalytic region of tyrosine kinase adaptor protein 1) were the most frequently overexpressed invadopodia regulators in GBM compared to non-tumor brain tissue." (PMID 33050088, 2020). "Furthermore, EDW01 displayed MT1-MMP and MMP-13 at the tumour-stromal boundary, but did not express these factors or MMP-2 and MMP-9 within the tumour mass itself." (PMID 33276802, 2020). "Although both MMP2 and MMP9 were present in primary tumors, SDS3 reduced the metastatic growth of VO-PyMT probing cells in the lungs of MMTV-PyMT mice without affecting primary tumor growth." (PMID 31727800, 2019). "Finally, the specificity of the PA-L1 protein variant to be cleaved and therefore activated by proteases other than its intended targets (MMP2, MMP9, and MMP14) and deliver 111In-LFE687A to tumor cells was not evaluated here." (PMID 30954944, 2019). "The tumor targeting of MAHNP-DOX was also confirmed by significantly lower accumulation and a higher IC50 in normal MCF-10 A breast cells, which are HER2 negative and normally have MMP-2 mostly in its inactive form." (PMID 29405790, 2018). "We found that in vitro treated 4T1 cell line with 25 μg/mL BDM significantly reduced the MMP‐2, MMP‐9 activities and adhesion of 4T1 cells to collagen I, fibronectin, and laminin which inhibited 77.7 % tumor incidence after inoculation without any effect in viability of cell line." (PMID 28211615, 2017). "Effects of FAK kinase inhibition may be attributed to attenuated cell migration, invasion, and lack of tissue remodeling enzymes such as MMP2, MMP9 and uPA, which may impact tumor metastasis." (PMID 28915654, 2017). "However, the expression of MMP-1, MMP-2, and MMP-9 was not different between primary NSCLC tumor and metastatic lymph node (MMP-1 and MMP-9 not shown)." (PMID 28915603, 2017). "Since aMMP2-SIP did not correlate with MMP2 expression levels, we investigated if aMMP2-SIP uptake could be affected by tumor microenvironmental factors like hypoxia, vasculature or perfused vessels." (PMID 26923459, 2016). "Upon depletion of Rab40b, the lack of MMP2 and MMP9 targeting could lead to reduced angiogenesis, thus inhibiting tumor growth." (PMID 27789576, 2016). "Further, levels of related MMPs including MMP1, MMP8, MMP14, MMP2 and MMP9 which have previously been shown to affect tumor cell invasion were not evaluated in these studies and could compensate for MMP13 levels." (PMID 25880591, 2015).
tumor (continued). "MMP2, which degrades the collagen IV-rich basal membrane as a necessary requisite for metastasis, was reduced in PTSMT, which indicates no major remodelling of extracellular matrix during tumour cell and endothelial proliferation." (PMID 24398114, 2014). "Further, our data imply that MMP-2 and -9 are not the only activities in the astrocyte CM that promote tumor cell invasion and metastasis because MMP chemical inhibition and blocking/neutralizing studies only attenuated about 50% of the tumor cell invasion." (PMID 24324647, 2013). "Development of TH2 cells, involved in responses against parasites (but detrimental in the setting of anti-tumor responses), is though to be induced by the lack of IL-12 as well as by IL-4, thymic stromal lymphopoietin (TSLP), and Matrix metalloproteinase 2 (MMP-2)." (PMID 24339825, 2013). "In this study, we aimed to correlate the expression of DSPP, OPN and BSP as well as three SIBLING-partners, matrix metalloproteinase-2 (MMP-2), matrix metalloproteinase-3 (MMP-3), and matrix metalloproteinase-9 (MMP-9), at histologically-negative margins of OSCCs with tumor recurrence." (PMID 22410369, 2012). "The alteration of endostatin (a potent angiogenesis inhibitor) and MT1-MMP (an activator of MMP2) was minor, which indicated that elevated tumor VEGF and increased MMP2 activity were not directly due to endostatin and MT1-MMP, whose detailed molecular mechanism remains to be elucidated." (PMID 20969807, 2010). "Indeed, we found a positive correlation between the expression of DDR1 and MMP2 in our patient cohort (data not shown), further supporting the important role of DDR1 for tumor invasion." (PMID 20799954, 2010). "EMMPRIN expression showed a significantly positive association with tumour size, depth of invasion, lymphatic invasion, expression of ki-67, MMP-2, MMP-9 and VEGF of tumours (P<0.05), but not with lymph node metastasis, UICC staging or differentiation (P>0.05)." (PMID 17088917, 2006). "Extracellular MMP inducer expression was positively correlated with tumour size, depth of invasion, lymphatic invasion, expression of ki-67, MMP-2, MMP-9 and VEGF of tumours (P<0.05), but not with lymph node metastasis, UICC staging or differentiation (P>0.05)." (PMID 17088917, 2006). "Separate analyzes of MMP1, MMP2, MMP3, MMP9, TIMP1, TIMP2, and MTC1 in plasma do not allow a prognostic prediction for tumour grading, staging, or metastasis, but certain combinations could be very helpful." (PMID 16901349, 2006). "However, immunostaining showed no relevant difference in the expression of gelatinases (MMP-2 and MMP-9) between the three types of tumour (not shown)." (PMID 11875720, 2002). "The analysis of metalloproteinase expression levels in tumor (MDA) and non-tumor (MCF 10A) cell lines cultured in a 3D collagen matrix following treatment with MeOH and DCM extracts represent a novelty into the modulatory effects of these extracts on MMP-9 and MMP-2." (PMID 39409699, 2024). "Histopathological examination of tumour tissue samples revealed a mixture of pigmented and non-pigmented spindle and epithelioid melanocytes, while according to immunohistochemistry, the tumours showed a strong immunopositivity for VEGF and MMP-10, and a moderate positivity for MMP-2 expression." (PMID 37104437, 2023). "Nevertheless, fibroblasts from tumor areas (C4) show higher expression of MMP-2 and TIMP-3, compared with fibroblasts from non-tumor areas from prostatectomies (C3), which indicate that more pronounced dramatic changes occur in the most intimate tumor microenvironment." (PMID 37108185, 2023). "Interestingly, CXCL12 enhances the expression of VE-cadherin, matrix metalloproteinase 2 (MMP2) and laminin5γ2 via CXCR4 in tumor cells (rather than endothelial cells), forming vascular-like channels that promote vascular mimicry (VM) formation and provide blood perfusion for HCC tissues." (PMID 34386499, 2021).